CLDN2 (claudin 2)
Diseases named in the same sentence as CLDN2 in open-access papers (continued):
Sharing a sentence is not in itself a finding about the gene and the disease.
breast carcinoma (32 papers, 2012 to 2025). "Loss of Afadin phenocopies Claudin-2 loss, resulting in impaired growth of breast cancer cells in soft agar and diminished lung or liver metastatic capacity." (PMID 30692208, 2019). "The concordant phenotypes exhibited by Claudin-2- and Afadin-deficient breast cancer cells suggest that a Claudin-2–Afadin signaling axis is important for the efficient formation of liver metastases." (PMID 30692208, 2019). "We first assessed the association of these proteins with histological subtypes of breast cancer, which revealed that both Claudin-2 and Afadin are significantly elevated in the TNBC compared with estrogen receptor (ER+) or HER2 subtypes." (PMID 30692208, 2019). "Decreased Claudin-2 expression is observed in breast cancers of increasing stage and grade and is associated with lymph node metastasis." (PMID 30692208, 2019). "In some breast cancer reduction in claudin-2 was associated with lymph node metastasis and higher clinical stage." (PMID 31726679, 2019). "Loss of afadin impaired colony formation of breast cancer cells in soft agar and reduced lung and liver metastasis, verifying the significance of the claudin-2/afadin complex." (PMID 31726679, 2019). "Knockdown of individual SFK members reveals that loss of Yes or Fyn induces Claudin-2 expression; whereas, diminished Lyn levels impairs Claudin-2 expression in breast cancer cells." (PMID 25823815, 2015). "Down-regulation of claudin-2 was significantly associated with lymph node metastasis in breast carcinomas by Western blot analysis, and with high clinical stage by immunohistochemistry." (PMID 23919729, 2013). "High expression of CLDN2 is closely associated with poor prognosis in breast cancer patients." (PMID 36895039, 2023). "CLDN2 expression in breast cancer tissue was reduced compared to that in normal breast tissue, and low CLDN2 expression was associated with lymph node metastasis and worsening clinical stage of breast cancer." (PMID 35053454, 2022). "Of note, claudin-2 has been reported to be part of a large protein complex, and a recent report demonstrated similar binding of claudin-2 protein with proteins implicated in cell polarity, cell-cell adhesion, trafficking and cell multiplication in breast cancer cells." (PMID 33622361, 2021). "In breast cancer, increased or decreased claudin-2 expression might be associated with different cancer types and stages." (PMID 31726679, 2019). "We next assessed the association of Claudin-2 and Afadin expression either alone or in combination with four breast cancer end points: breast cancer-specific survival (BCSS), relapse-free survival (RFS), liver metastasis-free survival (LiMFS), or lung metastasis-free survival (LuMFS)." (PMID 30692208, 2019). "For example, CLDN2 is an X-linked oncogene or tumor suppressor gene in breast cancer." (PMID 31467637, 2019). "Of note, claudin-2 was also shown to be enriched in macrophages associated with mammary tumors." (PMID 31726679, 2019). "Thus, the reduction in liver metastasis observed in mice injected with Afadin-deficient breast cancer cells is similar to that observed in mice injected with Claudin-2 knockdown cells, and both Afadin isoforms contribute to the formation of breast cancer liver metastases." (PMID 30692208, 2019). "CLDN2 increases the ability of breast cancer cells with liver metastases to adhere to the extracellular matrix by upregulating integrin expression." (PMID 36895039, 2023). "When we analyzed NGS data, we found and validated that the mRNA level of the breast cancer liver metastasis gene CLDN2 was significantly decreased in KK-LC-1 silenced cells." (PMID 36895039, 2023). "A similar result regarding increases in the expression of claudin-2 in primary breast cancer and reduced relapse-free survival was observed." (PMID 36232536, 2022). "Claudin-2 facilitates breast cancer cell interactions with the extracellular matrix and hepatocytes, which increases liver metastasis." (PMID 34079064, 2021).
breast carcinoma (continued). "Claudin-2 level is elevated in breast cancer liver metastasis, and it is responsible for adhering breast cancer cells to hepatocytes." (PMID 33262947, 2020). "In this study, we demonstrate that Claudin-2 expression in breast cancer cells is required for efficient anchorage-independent growth." (PMID 30692208, 2019). "Our findings indicate that signaling downstream from a Claudin-2/Afadin complex enables the efficient formation of breast cancer metastases." (PMID 30692208, 2019). "In this study, we identified Pdlim7 and Afadin as new interacting partners of Claudin-2 that contribute to the ability of breast cancer cells to grow in soft agar and form liver metastases." (PMID 30692208, 2019). "The ability of wild-type Claudin-2-expressing breast cancer cells to form liver metastases was increased 5.56-fold compared with the Claudin-2 ΔPDZ BD-expressing population." (PMID 30692208, 2019). "The PDZ-binding motif of Claudin-2 is required to enable the in vitro growth of breast cancer cells in soft agar and promote the formation of breast cancer liver metastases in vivo." (PMID 30692208, 2019). "We show that the PDZ-binding motif within Claudin-2 is dispensable for the ability of breast cancer cells to adhere to hepatocytes." (PMID 30692208, 2019). "As expected, weakly liver metastatic breast cancer cells overexpressing Claudin-2 exhibited a 3.26-fold to 4.20-fold increase in anchorage-independent colony formation compared with their respective vector controls." (PMID 30692208, 2019). "The ability of the Claudin-2 ΔPDZ BD mutant to rescue breast cancer cell/hepatocyte interactions indicates that this mutant localizes properly to the plasma membrane." (PMID 30692208, 2019). "Using metastatic breast cancer cells with elevated claudin-2 expression, they demonstrated that the last three C-terminal amino acids of claudin-2 (comprising the PDZ-binding motif) are necessary for anchorage-independent growth." (PMID 31726679, 2019). "Together, these data suggest that, like Claudin-2, Afadin functions to promote breast cancer liver metastasis." (PMID 30692208, 2019). "We next interrogated publicly available RNA sequencing data sets from The Cancer Genome Atlas (TCGA) for associations between CLDN2 and AFDN mRNA expression and breast cancer subtype and outcome." (PMID 30692208, 2019). "Our results confirm previous findings that Claudin-2 functions as a prognostic marker of breast cancer liver metastasis." (PMID 30692208, 2019). "Claudin-2 promotes breast cancer liver metastasis by enabling seeding and early cancer cell survival." (PMID 30692208, 2019). "Several PDZ domain-containing proteins were identified that interact with the PDZ-binding motif of Claudin-2 in liver metastatic breast cancer cells, including Afadin, Arhgap21, Pdlim2, Pdlim7, Rims2, Scrib, and ZO-1." (PMID 30692208, 2019). "In contrast, claudin-2 overexpression was shown to augment breast carcinoma metastasis to the liver." (PMID 31726679, 2019). "We first engineered weakly liver metastatic breast cancer cells to harbor an empty vector or overexpress either a wild-type or a mutant form of Claudin-2." (PMID 30692208, 2019). "Metastatic breast cancer cells showed a general increase in adhesion to the extracellular matrix, as claudin-2 promoted surface expression of α2β1- and α5β1-integrins." (PMID 31726679, 2019). "Our data also demonstrate that Claudin-2 and, to a greater extent, Afadin function as more general modulators of breast cancer metastasis to soft tissue sites, including the lung." (PMID 30692208, 2019). "In our breast cancer cohort (n = 86), CLDN2 mRNA transcripts were significantly and positively associated with miR-30a levels in cancerous tissues (Pearson correlation coefficient, 0.375; P = 0.0004)." (PMID 26918943, 2016). "The Lyn-selective kinase inhibitor, Bafetinib (INNO-406), acts to reduce Claudin-2 expression and suppress breast cancer liver metastasis." (PMID 25823815, 2015).
breast carcinoma (continued). "Given the role of this SFK-c-Fos pathway in regulating Claudin-2 expression, we predicted that pan-SFK inhibitors would, in fact, enhance breast cancer metastasis to the liver, through the transcriptional up-regulation of Claudin-2." (PMID 25823815, 2015). "We evaluated the effect of several Src Family Kinase (SFK) inhibitors or knockdown of individual SFK members on Claudin-2 expression in breast cancer cells." (PMID 25823815, 2015). "In contrast, Claudin-2 expression has been reported to decrease in breast cancers of increasing tumor grade and stage, and low Claudin-2 levels are associated with lymph node metastasis." (PMID 25823815, 2015). "The mechanisms through which Claudin-2 enhances breast cancer metastasis to the liver involve enhanced seeding and early-stage survival." (PMID 25823815, 2015). "Neutralizing antibody targeting α5β1 or α2β1 complexes can block claudin-2-mediated adhesion to fibronectin and type IV collagen, and reduce the ability of breast cancer cells to metastasize to the liver." (PMID 25885919, 2015). "We then used chromatin immunoprecipitation assays to monitor the recruitment of c-Fos to the human CLDN2 promoter in MDA-MB-231 breast cancer cells following treatment with SFK inhibitors." (PMID 25823815, 2015). "Uniformly, Bafetinib treatment reduced Claudin-2 levels in human breast cancer cells and liver-metastatic mouse breast cancer cells." (PMID 25823815, 2015). "Claudin-2 has been shown to mediate tumor cell/hepatocyte interactions and the ability of breast cancer cells to form liver metastases in vivo." (PMID 25871476, 2015). "Claudin-2 mediates breast cancer metastasis to the liver, at least partially, by enhancing adhesion to ECM proteins, such as fibronectin and type IV collagen, which are abundant in the liver." (PMID 25885919, 2015). "In liver metastases of breast cancer, claudin-2 expression was found to be elevated in comparison to primary tumour 72,73." (PMID 25598217, 2015). "The roles of claudin proteins in breast cancer progression are complicated, and claudin-2 expression is down-regulated compared with normal tissues." (PMID 25885919, 2015). "Immunohistochemical analyses have shown that claudin-2 is detected in all liver metastases and weakly expressed in primary human breast cancers." (PMID 25885919, 2015). "This study reveals that pan inhibition of SFK signaling pathways significantly elevated Claudin-2 expression levels in breast cancer cells." (PMID 25823815, 2015). "Our previous studies revealed that Claudin-2 expression was selected for in aggressively liver-metastatic breast cancer cells; whereas, the expression of other cell-cell adhesion molecules was decreased." (PMID 25823815, 2015). "Taken together our observations reveal a critical role for Lyn in promoting Claudin-2 expression in breast cancer cells, highlighting the potential of this specific SFK family member as an important therapeutic target in the management of liver metastasis." (PMID 25823815, 2015). "Claudin-2 functions at an early stage following the seeding of the liver to promote breast cancer cell colonization and metastatic formation." (PMID 25598217, 2015). "Our current findings reveal, for the first time, that signaling via Src family kinases can control Claudin-2 expression in breast cancer cells." (PMID 25823815, 2015). "Take together, these results revealed novel roles of claudin-2 in promoting breast cancer adhesion to the ECM and breast cancer metastasis to the liver." (PMID 25885919, 2015). "We observed an increase in Claudin-2 levels when human and mouse breast cancer cells were individually treated with each SFK inhibitor." (PMID 25823815, 2015). "The objective of our current study is to define the regulatory mechanisms controlling Claudin-2 expression in breast cancer cells." (PMID 25823815, 2015).
breast carcinoma (continued). "We further demonstrated that Claudin-2 is functionally involved in liver metastasis and highly expressed in liver metastases from breast cancer patients." (PMID 25823815, 2015). "As observed with human (MDA-MB-231 and BRC31) and mouse (2776) breast cancer cells, we observed an increase in Claudin-2 levels when GCRC1735 PDX cells were treated with Dasatinib." (PMID 25823815, 2015). "In a previous study, Kim reported that down-regulation of CLDN2 in breast carcinomas was related to advanced disease and lymph node metastasis." (PMID 25393310, 2014). "It was reported that EGF signaling induced claudin-2 expression which promoted colonization of mammary tumor cells." (PMID 22824143, 2012). "Past studies show that high claudin-2 expression in breast cancer cells increases liver adhesion." (PMID 40510151, 2025). "Besides, KK-LC-1 was also significantly positively correlated with the expression of the breast cancer liver metastasis regulatory gene CLDN2 and can regulate its expression by competitively binding to RBP-HNRNPL with CLDN2 mRNA." (PMID 36895039, 2023). "Furthermore, claudin-2 is detected in 52% of all breast carcinomas and is a known promoter of breast cancer metastasis." (PMID 36014839, 2022). "For example, CLDN2 is highly expressed in liver metastasis tissues of breast cancer and enhances adhesion to extracellular matrix through type IV collagen and fibronectin, thereby promoting liver metastasis of breast cancer cells." (PMID 34405008, 2021). "Evidence showed that as a PDZ domain containing protein, ARHGAP21 could interact with the PDZ-binding motif of Claudin-2, in such way promoted breast cancer liver metastasis." (PMID 34211100, 2021). "Immunoprecipitation experiments revealed that RIMS2 may promote anchorage-independent growth and colony formation of liver metastatic breast cancer cells by binding with claudin-2 gene via a PDZ-binding motif." (PMID 34211824, 2021). "Moreover, combining Claudin-2 and Afadin as prognostic markers better predicts the potential of breast cancer to metastasize to soft tissues." (PMID 30692208, 2019). "Determining whether Claudin-2 directly or indirectly interacts with Afadin in liver metastatic breast cancer cells will require additional experimentation." (PMID 30692208, 2019). "Importantly, expression of either wild-type or a ΔPDZ BD mutant form of Claudin-2 fully restores the ability of these breast cancer cells to adhere to primary hepatocytes." (PMID 30692208, 2019). "Finally, we explored the potential of Claudin-2 and/or Afadin as biomarkers to predict metastasis in primary breast cancer." (PMID 30692208, 2019). "Our results demonstrate a functional requirement for Afadin in promoting breast cancer metastasis to the lungs or liver through a mechanism that may involve complex formation with Claudin-2." (PMID 30692208, 2019). "To investigate whether Claudin-2 conferred anchorage-independent growth to liver metastatic 4T1 breast cancer cells, we assessed the ability of weakly and aggressively liver metastatic cell lines to grow in soft agar." (PMID 30692208, 2019). "Thus, both Claudin-2 and Afadin not only contribute to the formation of breast cancer liver metastases but also function to promote breast cancer lung metastasis." (PMID 30692208, 2019). "To investigate potential binding partners that interact via the PDZ-binding motif of Claudin-2, we generated hemagglutinin (HA)-tagged versions of both wild-type and the Claudin-2 ΔPDZ BD mutant and expressed them in liver-aggressive 4T1 breast cancer cells (2776)." (PMID 30692208, 2019). "To determine whether the metastasis-promoting effects of Claudin-2 and Afadin were restricted to the liver, we next assessed their contribution to the formation of breast cancer lung metastases." (PMID 30692208, 2019). "Thus, the PDZ-binding motif in Claudin-2 is required for anchorage-independent growth of aggressively liver metastatic breast cancer cells." (PMID 30692208, 2019).
breast carcinoma (continued). "Finally, our results support a role for Afadin, in cooperation with Claudin-2, in promoting the ability of breast cancer cells to metastasize to soft tissues such as the liver and lungs." (PMID 30692208, 2019). "Thus, claudin-2 in the metastatic breast cancer cells can bind to claudin-2 on hepatocytes, thereby promoting their adhesion to the liver." (PMID 31726679, 2019). "Osteosarcoma and breast cancer—Interestingly, in some tumors, claudin-2 expression is decreased." (PMID 31726679, 2019). "Claudin-2 expression is elevated in liver metastases compared to primary breast cancer cells." (PMID 31726679, 2019). "In breast cancer, Claudin-2 expression is detected in 52% of breast carcinomas." (PMID 30692208, 2019). "We also assessed whether Bafetinib treatment had the same effect on Claudin-2 levels in multiple breast cancer cell models." (PMID 25823815, 2015). "Thus, we investigated the involvement of SFKs in the regulation of Claudin-2 expression and liver metastatic ability of breast cancer cells." (PMID 25823815, 2015). "Moreover, decreased levels of claudin-2 are observed in high-grade breast cancer, suggesting that claudin-2 plays a suppressive role in breast cancer." (PMID 25885919, 2015). "Therefore, α2β1 or α5β1 complexes can promote the ability of breast cancer cells to metastasize to the liver, at least partially, via the claudin-2 signaling pathway." (PMID 25885919, 2015). "Finally, Claudin-2 has recently been described as a prognostic biomarker able to predict the likelihood of breast cancer recurrence specifically to the liver." (PMID 25823815, 2015). "Our previous studies demonstrated that Claudin-2 is functionally involved in breast cancer metastasis to the liver and a recent independent study has highlighted the potential of Claudin-2 as a prognostic biomarker that is able to predict the liver metastatic potential of primary breast tumors." (PMID 25823815, 2015). "Given the central role Lyn plays in regulating Claudin-2 expression, kinase inhibitors that specifically target Lyn could potentially reduce Claudin-2 expression and breast cancer liver metastasis." (PMID 25823815, 2015). "It has been reported that claudin-2 facilitates the cell-matrix adhesions by increasing the cell surface expression of α2β1 and α5β1-integrin complexes in breast cancer cells, promoting the formation of breast cancer liver metastases." (PMID 26081244, 2015). "However, little is known about the mechanisms that govern Claudin-2 expression in breast cancer cells." (PMID 25823815, 2015). "In agreement with our immunoblotting results, quantitative real-time PCR showed that CLDN2 mRNA levels are increased in both human and mouse breast cancer cells following treatment with pan-SFK inhibitors (1.73 – 3.33 fold induction for Dasatinib; 6.51 – 30.7 fold induction for PP2)." (PMID 25823815, 2015). "However, despite reduced expression in primary breast cancers, we have recently demonstrated that Claudin-2 functions as a key mediator of breast cancer metastasis to the liver." (PMID 25823815, 2015). "Therefore, we preliminarily concluded that KK-LC-1 may promote breast cancer liver metastasis by regulating the expression of CLDN2." (PMID 36895039, 2023). "We next assessed whether pan-SFK inhibitors affected transcription of CLDN2 in breast cancer cells." (PMID 25823815, 2015). "Thus, the Dasatinib-induced increase in Claudin-2 expression may promote breast cancer survival and enhanced formation of liver metastases." (PMID 25823815, 2015). "As adhesion molecules such as claudin-2 are reported to promote breast cancer liver metastasis by facilitating tumor cell interactions with hepatocytes, we speculate that there must be other molecules regulated by JMJD2A that mediate breast cancer preferably liver metastasis." (PMID 24886710, 2014).